ACE (angiotensin I converting enzyme)
Diseases named in the same sentence as ACE in open-access papers (continued):
Sharing a sentence is not in itself a finding about the gene and the disease.
psoriasis (29 papers, 2012 to 2025). An autoimmune condition characterized by red, well-delineated plaques with silvery scales that are usually on the extensor surfaces and scalp. "Several medications have been linked to the onset or worsening of psoriasis, including angiotensin-converting enzyme (ACE) inhibitors, angiotensin II receptor blockers (ARBs), lithium, antimalarial agents, and nonsteroidal anti-inflammatory drugs (NSAIDs)." (PMID 41226338, 2025). "This case underscores the potential for ACE inhibitors to trigger psoriasis flare-ups in susceptible individuals, highlighting the need for clinicians to be vigilant when prescribing these medications to patients with a history of psoriasis." (PMID 39364528, 2024). "This case underscores the potential for ACE inhibitors, such as lisinopril, to exacerbate psoriasis in susceptible individuals." (PMID 39364528, 2024). "Certain medications, including Angiotensin-Converting Enzyme (ACE) inhibitors, have been implicated as potential triggers for psoriasis flare-ups." (PMID 39364528, 2024). "It is worth noting that elevated ACE activity is associated with more severe psoriasis and a higher prevalence of cardiovascular comorbidities among this population." (PMID 37998534, 2023). "Although studies reporting the possible association between ACE inhibitor use and psoriasis exist, the results have been inconsistent." (PMID 33976340, 2021). "The results of our meta-analysis indicate a significant association between ACE inhibitor use and psoriasis incidence." (PMID 33976340, 2021). "Odds ratios (ORs) and 95% confidence intervals (CIs) were calculated to evaluate the strength of the association between ACE inhibitor use and psoriasis incidence." (PMID 33976340, 2021). "For the association of ACE inhibitor use with psoriasis incidence, eight studies with a total of 54,509 patients with a psoriasis diagnosis were included in the meta-analysis." (PMID 33976340, 2021). "In the subgroup analyses by continent and climate, risk of psoriasis related to ACE inhibitor use was higher in Asia and in a dry climate." (PMID 33976340, 2021). "Nevertheless, this study is valuable in that it is the first systematic review and meta-analysis to evaluate the association between ACE inhibitor use and psoriasis." (PMID 33976340, 2021). "By combining the statistically insignificant findings of several studies, this study revealed significant associations between ACE inhibitor use and psoriasis." (PMID 33976340, 2021). "A meta-analysis of the association of angiotensin-converting enzyme (ACE) gene polymorphisms with psoriasis susceptibility showed that the polymorphisms were associated with the risk of psoriasis in Asians." (PMID 34589554, 2021). "Previously, a meta-analysis conducted in ten studies and checking for the association between ACE I/D polymorphisms and psoriasis susceptibility suggested that the ID genotype was a predisposing factor for psoriasis in East Asian subjects." (PMID 31914957, 2020). "A dichotomous analysis was carried out by RevMan 5.3 using crude odds ratio (OR) and 95% confidence interval (CI) to investigate the association between ACE I/D polymorphisms and the risk of psoriasis." (PMID 31914957, 2020). "The present meta-analysis investigated the association between ACE I/D polymorphisms with psoriasis susceptibility and also the distribution of genotypes in psoriatic patients." (PMID 31914957, 2020). "Some drugs, such as beta-blockers, lithium, NSAIDs, tetracycline and synthetic antimalarials have apparent causal relationship with psoriasis while others like ACE inhibitors, interferons and some antifungals have been associated with psoriasis but the relationship is less well-defined." (PMID 40748586, 2025). "The immunomodulatory effects of ACE inhibitors may interact with the underlying inflammatory pathways involved in psoriasis, potentially leading to an exacerbation of symptoms." (PMID 39364528, 2024).
psoriasis (continued). "Interestingly, other ACE inhibitors, including ramipril and perindopril, have also been implicated in psoriasis exacerbations." (PMID 39364528, 2024). "There is a potential association between psoriasis incidence and polymorphisms in the ACE gene." (PMID 37998534, 2023). "Moreover, serum level of ACE is increased among psoriasis patients, and directly correlates with increased risk of cardiovascular comorbidities, including subclinical atherosclerosis." (PMID 35566548, 2022). "Conversely, the ACE inhibitors administration in patients with personal history of psoriasis may be associated with psoriasis exacerbation." (PMID 35566548, 2022). "Further analysis using subgroups of the West Asia and the East Asia showed that higher association between ACE inhibitor use and psoriasis incidence was found in studies conducted in West Asia (OR 3.45, 95% CI 2.05–5.79) compared to those in East Asia (OR 1.47, 95% CI 1.25–1.73)." (PMID 33976340, 2021). "Therefore, we investigated the association between ACE inhibitor use and psoriasis incidence through a systematic literature review and meta-analysis." (PMID 33976340, 2021). "Because bradykinin is seemingly the main mechanism of both ACE inhibitor-induced psoriasis and cough, the higher incidence of ACE inhibitor-related cough in Asians could explain the high risk of psoriasis in Asians." (PMID 33976340, 2021). "Therefore, we aimed to evaluate the association between ACE inhibitor use and psoriasis incidence through a systematic literature review and meta-analysis." (PMID 33976340, 2021). "Our results reveal a significant association between ACE inhibitor use and psoriasis incidence." (PMID 33976340, 2021). "According to another study, angiotensin-converting enzyme (ACE) insertion/deletion (I/D) gene polymorphism may affect susceptibility to early-onset psoriasis, yet its role in HT pathogenesis needs further evaluation due to contradictory study results." (PMID 34445769, 2021). "ACE inhibitors and loop diuretics could increase the risk of psoriasis." (PMID 39567981, 2024). "In addition, because environmental factors may affect the association between ACE inhibitor use and psoriasis, subgroup analyses by study design, continent and climate were also performed." (PMID 33976340, 2021). "A hypothesis for the association between ACE inhibitor use and psoriasis is related to bradykinin." (PMID 33976340, 2021). "The results of the meta-analysis showed that ACE I/D polymorphism may be associated with psoriasis susceptibility, while ID genotype seemed to have a protective role in Caucasian patients affected by psoriatic arthritis and in studies with hospital-based controls." (PMID 31914957, 2020). "This case also highlights the need for clinicians to remain vigilant for dermatological side effects in patients receiving ACE inhibitors, particularly those with a personal or family history of psoriasis." (PMID 39364528, 2024). "This case study not only contributes to the limited literature on ACE inhibitor-induced psoriasis but also highlights the importance of personalized medicine." (PMID 39364528, 2024). "Given the widespread use of ACE inhibitors for managing cardiovascular conditions, the potential for these drugs to induce or exacerbate psoriasis has significant implications for clinical practice." (PMID 39364528, 2024). "This case underscores the potential for ACE inhibitors to exacerbate psoriasis, particularly in patients with a history of the condition, highlighting the need for careful consideration of medication choices in this patient population." (PMID 39364528, 2024). "Given the widespread use of ACE inhibitors for managing cardiovascular conditions, the potential for these drugs to trigger psoriasis flare-ups poses significant implications for patient care." (PMID 39364528, 2024). "The excessive activity of ACE in patients with COVID-19 can exacerbate psoriasis and lead, in the known cases, to a higher occurrence of cardiovascular events." (PMID 37998534, 2023).
psoriasis (continued). "A recent review also showed that, in addition to beta-blockers, psoriasis can also be exacerbated in patients taking angiotensin-converting enzyme (ACE) inhibitors or angiotensin II receptor blockers (sartans)." (PMID 35743091, 2022). "The pooled OR for psoriasis incidence among ACE inhibitor users was 1.52 (95% CI, 1.16–2.00) compared to that among non-users." (PMID 33976340, 2021). "Although a considerable volume of data supporting induction or aggravation of psoriasis because of angiotensin-converting enzyme (ACE) inhibitor use exists, it remains insufficient for definitive conclusions." (PMID 33976340, 2021). "Based on our results, ACE inhibitor users should be carefully screened for cutaneous adverse events, particularly psoriasis." (PMID 33976340, 2021). "Second group of drugs have considerable yet insufficient data supporting incidence or aggravation of psoriasis, such as ACE inhibitors, interferons, and terbinafine." (PMID 33976340, 2021). "Increased levels of serum ACE, IL-6 and IL-8 in psoriasis patients were due to the important role of ACE in inflammation." (PMID 31914957, 2020). "Herein, a meta-analysis assessed the association of angiotensin-converting enzyme gene insertion/deletion (ACE I/D) polymorphism and psoriasis susceptibility." (PMID 31914957, 2020). "Polymorphisms in both ACE and other angiotensinogen genes have been associated with susceptibility to inflammatory diseases such as SLE and psoriasis with frequent tonsillitis." (PMID 23437094, 2013). "Comparative studies between ACE inhibitors and other classes of antihypertensive drugs could provide valuable insights into safer alternatives for psoriasis patients." (PMID 39364528, 2024). "However, the role of ACE inhibitors in precipitating or worsening psoriasis is less well documented, making it a critical area for further investigation." (PMID 39364528, 2024). "Further research is needed to elucidate the precise mechanisms by which ACE inhibitors may induce psoriasis and to explore whether certain patient populations are more at risk than others." (PMID 39364528, 2024). "However, the role of angiotensin-converting enzyme (ACE) inhibitors, such as lisinopril, in precipitating psoriasis flare-ups remains less clear, possibly due to fewer studies and clinical reports." (PMID 39364528, 2024). "This case highlights the need for further research into the relationship between ACE inhibitors and psoriasis, contributing to the ongoing discourse on drug-induced dermatological conditions and emphasizing the value of personalized medicine in optimizing patient care." (PMID 39364528, 2024). "Epidemiological data, though limited, suggest that ACE inhibitors may also contribute to psoriasis exacerbations, albeit less frequently than other medications." (PMID 39364528, 2024). "Clinicians should exercise caution when prescribing ACE inhibitors to patients with a history of psoriasis, consider alternative antihypertensive therapies when appropriate, and closely monitor those who require ACE inhibitors to ensure early detection and management of any flare-ups." (PMID 39364528, 2024). "ACE inhibitor user group had a higher association with psoriasis incidence compared to the non-user group (Odds ratio (OR) 1.52, 95% confidence interval (CI) 1.16–2.00)." (PMID 33976340, 2021). "Moreover, psoriasiform eruptions and exacerbation of pre-existing psoriasis were reported in patients receiving other ACE inhibitors such as ramipril and lisinopril." (PMID 33976340, 2021). "In addition, fish oil supplementation can be considered in the treatment regimen of psoriasis subjects in case of COVID-19 infection, as it can inhibit ACE activity and decrease symptoms in psoriasis subjects." (PMID 34938746, 2021).
psoriasis (continued). "A significant difference between ACE polymorphisms in patients with/without family history for the disease [OR = 1.44; 95%CI: 1.24, 1.67; P < 0.001] and also in patients mild/severe psoriasis [OR = 0.70; 95%CI: 0.55, 0.88; P = 0.002] was identified." (PMID 31914957, 2020). "With regard to ethnicity, the analyses showed that there was no risk of psoriasis related to ACE I/D polymorphisms in East Asian populations, but the presence of ID genotype had a slight protective effect against the disease [OR = 0.82; 95%CI: 0.69, 0.97]." (PMID 31914957, 2020). "This shows an important role of ACE in the pathogenesis of psoriasis." (PMID 31914957, 2020). "A possible explanation for its role in psoriasis may be related to the fact that the ACE II genotype reduces ACE activity in skin and may prolong or augment activation of the kallikrein–kinin system, thereby increasing the risk for psoriasis." (PMID 31914957, 2020). "Furthermore, it has been investigated that the use of ACE inhibitors can create or aggravate psoriasis in clinical practice." (PMID 31914957, 2020). "Angiotensin I-converting enzyme (ACE) gene polymorphisms have been correlated with susceptibility to multiple inflammatory diseases, including psoriasis and systemic lupus erythematosus; furthermore, angiotensin II (AngII) pathway is known to play a vital part in SS." (PMID 28336767, 2017). "However, the precise mechanism by which ACE inhibitors or sartans could trigger psoriasis is still unknown." (PMID 35743091, 2022). "The ACE inhibitor users within the dry climate subgroup showed a considerably higher risk of psoriasis incidence compared to the non-users (OR 3.45, 95% CI 2.05–5.79), whereas the analysis of the temperate climate subgroup showed marginal significance (p = 0.05)." (PMID 33976340, 2021). "Therefore, psoriasis due to ACE inhibitor use could involve more complex processes." (PMID 33976340, 2021). "The discovery of RAGE and its role in the inflammatory response led some researchers to the idea that certain synthetic medications, such as ACE inhibitors (ACEI) that have anti-RAGE effects can be used on a broader spectrum of diseases, including psoriasis." (PMID 24170986, 2013). "In conclusion, while the connection between ACE inhibitors and psoriasis flare-ups is not yet fully established, this case contributes to the growing body of evidence suggesting a potential link." (PMID 39364528, 2024). "The patient had been stable for several years with no significant psoriasis symptoms until the ACE inhibitor was introduced, indicating a probable drug-induced exacerbation, supported by the temporal association between the drug initiation and the flare-up." (PMID 39364528, 2024). "The exact mechanism behind ACE inhibitors precipitating psoriasis flare-ups is not fully understood." (PMID 39364528, 2024). "Some drugs have been shown to induce and exacerbate psoriasis, including lithium, beta-blockers, tetracyclines, non-steroidal anti-inflammatory agents, imiquimod, angiotensin-converting enzyme (ACE) inhibitors, and calcium channel blockers." (PMID 34371756, 2021). "Discontinuation of the ACE inhibitor led to a gradual improvement in symptoms, managed with topical corticosteroids and emollients, and switching to an alternative antihypertensive medication resulted in no further exacerbation of psoriasis." (PMID 39364528, 2024). "While the exact mechanism by which ACE inhibitors might trigger or worsen psoriasis is not fully understood, it is hypothesized that the immunomodulatory effects of these medications may interfere with the inflammatory pathways involved in psoriasis." (PMID 39364528, 2024).
renal fibrosis (29 papers, 2014 to 2025). A final common manifestation of a wide variety of chronic kidney diseases characterized by glomerulosclerosis and tubulointerstitial fibrosis. "Our results demonstrate that inhibition of ACE protects renal fibrosis by suppressing DPP-4-associated mesenchymal transformations and elevating the gene expression of antifibrotic microRNAs in the kidneys of diabetic mice." (PMID 32085655, 2020). "TGFβ is also associated with activity of ACE in renal fibrosis and disease progression." (PMID 29030610, 2017). "A mouse-based animal experiment showed that the use of RAAS inhibitors, ACE, or an angiotensin-converting enzyme inhibitor significantly reduced renal fibrosis." (PMID 40070584, 2025). "Currently, commercially available treatments for renal fibrosis include angiotensin-converting enzyme (ACE) inhibitors, angiotensin II receptor blockers (ARBs), and renin inhibitors." (PMID 38970048, 2024). "In STZ-induced diabetic nephropathy rats, exogeneous Ac-SDKP reduced renal fibrosis, and addition of ACE inhibitor ramipril further improved the fibrosis by repressing the metabolism of Ac-SDKP." (PMID 36362069, 2022). "For example, in reflux nephropathy (RN), angiotensin-converting enzyme (ACE) overexpression induces tubulointerstitial damage via increased extracellular matrix (ECM) component production; ACE inhibition may thus suppress renal fibrosis in this context." (PMID 33299464, 2020). "Ours is the first study to compare different RAASi and suggest that monotherapy with aldosterone antagonists might be as effective as, or even more effective than ACE inhibitors or angiotensin II receptor blockers in preventing the progression of renal fibrosis in DKD." (PMID 30324679, 2019). "Activation of any of the components of the pressor arm [AngII (angiotensin II)/ACE (angiotensin-converting enzyme)/AT1Rs (AngII type 1 receptors)] of renin angiotensin system (RAS) instigates cardiovascular and renal fibrosis." (PMID 28727756, 2017). "In the same study, high dose angiotensin-converting enzyme (ACE) inhibitor Enalapril normalized blood pressure, prevented renal fibrosis, and virtually eliminated albuminuria." (PMID 28746409, 2017). "Conversely, ACE inhibitors, AT1R antagonists, TGF-β neutralizing antibodies and TGF-β suppression by siRNA attenuate renal fibrosis." (PMID 25148511, 2014). "The primary finding was that fructose worsened the renal tubular injury (as noted by ACE staining) and resulted in marked tubulointerstitial inflammation and a tendency for worse renal fibrosis (although the latter two findings were not significant)." (PMID 30005632, 2018).
lung disease (28 papers, 2010 to 2025). "Previous studies had found that changes in ACE gene expression in plasma were strongly associated with the onset of a variety of lung diseases." (PMID 39188047, 2024). "The decrease of ACE2 expression and the deletion allele of ACE may cause the pulmonary disease to progress as an increase of ACE2, and an alteration in the ACE activity may be advantageous for the pulmonary disease progression." (PMID 34803443, 2021). "In this manner, differences in ACE expression and activity between individuals could explain differing susceptibilities to smoking-induced lung diseases and phenotypes via modulating levels of AcPGP." (PMID 29202450, 2017). "Pulmonary capillary ACE activity has been proven to be a reliable index of endothelial dysfunction in variable pulmonary diseases." (PMID 33233715, 2020). "Direct evidence has shown that decreased pulmonary capillary endothelium-bound (PCEB)-ACE activity is correlated with the severity of lung disease in ARDS patients." (PMID 33238910, 2020). "Additionally, the population was homogeneous in terms of cardiovascular drug use (ACE inhibitors, sartans, beta-blockers, diuretics, statins), history of cardiovascular surgery, and other comorbidities such as hematological and oncological disorders, thyroid dysfunction, pulmonary disease." (PMID 41226653, 2025). "The increase in the activity of ACE in bronchoalveolar lavage (BAL) fluid and serum was considered to be a marker of lung injury in a number of pulmonary diseases because its concentration in the serum is only a very small fraction of the total body ACE activity." (PMID 27275272, 2015).